GADD45A (growth arrest and DNA damage inducible alpha)
Diseases named in the same sentence as GADD45A in open-access papers (continued):
Sharing a sentence is not in itself a finding about the gene and the disease.
prostate carcinoma (27 papers, 2005 to 2025). A carcinoma that arises from epithelial cells of the prostate gland. "Induction of GADD45A by SAHA treatment in prostate cancer cell lines could mean that downregulation is associated with histone deacetylation and altered chromatin structure." (PMID 17280610, 2007). "For example, GADD45A is a vitamin D target gene in the context of prostate cancer cells, and its involvement in MAPK signaling has been reported in colon cancer cells." (PMID 37834080, 2023). "Among them, GADD45A is well known for inhibiting cell growth in various types of cancers, including prostate cancer." (PMID 33406670, 2021). "Isoliquiritigenin, a chalcone found in licorice, induces G2/M phase arrest and apoptosis in prostate cancer cells, with an increase in GADD45A expression." (PMID 33406670, 2021). "When the expression of GADD45A, which was targeted by tRF-315, was inhibited, the cisplatin-induced increase in the proportion of cells in the subG1 phase in prostate cancer was reduced." (PMID 33406670, 2021). "Current studies have shown that abnormal expression of the GADD45A gene is closely related to lung, breast, pancreatic and prostate cancers." (PMID 32181475, 2020). "The appearance of known targets of methylation, CCND2, CD44, ECAD and GADD45A, demonstrated the success of this technique in identifying (potential) targets of methylation in prostate cancer." (PMID 17453001, 2007). "In spite of the response to 5-aza-dC, bisulfite sequencing revealed the GADD45A promoter to be unmethylated in prostate cancer cell lines and prostate cancer tissues with low expression." (PMID 17280610, 2007). "Treatment with a combination of 5-aza-dC and SAHA increased expression of GADD45A in two prostate cancer cell lines, PC3 and DU145." (PMID 17280610, 2007). "This suggests that the inhibition of GADD45A may prevent apoptosis in prostate cancer cells, implying the cell growth regulatory function of GADD45A." (PMID 33406670, 2021). "In addition, GADD45A methylation in DNA in serum has been suggested as a biomarker for prostate cancer in combination with PSA, since it can clinically distinguish prostate cancer." (PMID 33406670, 2021). "Several therapeutic aids that can be used to treat prostate cancer target GADD45A." (PMID 33406670, 2021). "Furthermore, GADD45A expression has been shown to be induced by genistein treatment of human prostate cancer cell lines." (PMID 18847459, 2008). "GADD45A found downregulated in prostate cancers in our study is a well-established BRCA1 target." (PMID 17280610, 2007). "As GADD45A plays a role in genomic stability and tumorigenesis, some studies explored the role of GADD45A in various cancers, such as prostate cancer, ovarian cancer, esophageal cancer and malignant gliomas, which revealed different GADD45A expressions in various carcinoma tissues." (PMID 30128181, 2018). "In other study, authors found an increase in the GADD45A and GADD45B in docetaxel- and estramustine-treated prostate cancer cells which suggest their affects in the induction of apoptosis." (PMID 29386013, 2018). "Our previous studies suggest that AT2R-mediated apoptosis was mediated by p38 MAPK and caspase-3 and downregulation of Gadd45a, TRAIL-R2, and harakiri Bcl-2-interacting protein (HRK) in prostate cancer cells." (PMID 28599664, 2017). "Real-time RT-PCR revealed GADD45A, MX1, EPB41L3/DAL1, and FBLN1 as generally downregulated in prostate cancer, whereas HOXB13 and EPB41L4B were upregulated." (PMID 17280610, 2007).
prostate carcinoma (continued). "Taken together, our results demonstrated that TRAIL-R2, Gadd45a and HRK may be novel target genes for further study of the mechanism of AT2R-mediated apoptosis in prostate cancer cells." (PMID 24658029, 2014). "One unknown question that remains undiscovered is the main signaling pathways or factors in apoptosis induced by AT2R, which can be affected by Gadd45a, TRAIL-R2 and HRK in prostate cancer cells." (PMID 24658029, 2014). "The author has suggested that each MAPK plays a different role in GADD45A induction and G1 arrest by fucoxanthin based on the negative regulation of p38 MAPK resulting in increased GADD45A expression along with other observations in prostate cancer cells." (PMID 24351910, 2013). "The induction of apoptosis mediated by GADD45A, GADD45B, PA25, and PIG11 could be another molecular mechanism by which Taxotere and/or Furtulon inhibit the growth of prostate cancer cells." (PMID 15656911, 2005). "However, in colon cancer cells, G1 arrest occurs via p21 upregulation and pRB phosphorylation without altering cyclin D/CDK4 levels, while prostate cancer models implicate GADD45A/JNK signaling." (PMID 40735485, 2025). "Thus the growth inhibitory effect exhibited by fucoxanthin may in part be due to a GADD45A-dependent pathway and the enhanced GADD45A expression and G1 arrest are positive regulated by SAPK/JNK in prostate cancer cells." (PMID 24351910, 2013). "GADD45A, which is also induced by BRCA-dependent pathways, was significantly decreased in prostate cancers compared to noncancerous tissues, with the lowest levels in 'both' cancers." (PMID 17280610, 2007).
melanoma (19 papers, 2013 to 2025). A malignant, usually aggressive tumor composed of atypical, neoplastic melanocytes. "Our data showed that cisplatin stimulated the expression of GADD45A in melanoma cells to cause enhanced G2/M arrest." (PMID 29515153, 2018). "Additionally, to further verify whether down-regulation of GADD45A could enhance DNA damage associated with cisplatin treatment in melanoma, we assayed for phosphorylated H2AX (γ-H2AX), an early phase marker of DNA double strand break (DSB)." (PMID 29515153, 2018). "The inhibition of GADD45A made melanoma cells more sensitive to cisplatin, enhanced cisplatin-induced DNA damage, and induced apoptosis." (PMID 40429988, 2025). "It has been shown that TP-472 treatment leads to upregulation of GADD45A, the pro-apoptosis gene in melanoma cells." (PMID 35883603, 2022). "A constitutive activation of the ERK kinase, which can be frequently found in melanoma tumors, leads to a downregulation of GADD45A." (PMID 36497117, 2022). "Inactivation of GADD45A enhanced cisplatin-induced DNA damage, cell cycle arrest and sensitized melanoma cells to cisplatin treatment." (PMID 29515153, 2018). "In this study, we focused on exploring the importance of GADD45A induction in melanoma cells post cisplatin treatment." (PMID 29515153, 2018). "On the contrary, suppression of GADD45A released the cells from G2/M arrest to significantly boost cisplatin-induced apoptosis of melanoma cells." (PMID 29515153, 2018). "Altogether, these results demonstrated that GADD45A inhibition was able to sensitize melanoma cells to cisplatin-induced apoptosis in-vitro." (PMID 29515153, 2018). "Our finding supported the view that GADD45A was a key factor determining melanoma’s sensitivity to cisplatin through modulation of DNA repair." (PMID 29515153, 2018). "In this study, we found that cisplatin dramatically induced the expression of GADD45A in melanoma and that inhibition of GADD45A sensitized melanoma cells to cisplatin." (PMID 29515153, 2018). "Downregulation of GADD45A sensitized melanoma cells to cisplatin and dramatically increased DNA double strand break." (PMID 29515153, 2018). "However, STX140 (100 nM) significantly (p < 0.05) increased CDKN1A and GADD45A expression in resistant melanoma cells." (PMID 37511073, 2023). "The authors of the study conclude that GADD45A could play a role in the resistance to classical chemotherapies often occurring in melanoma through a hyperactivation of the DNA damage response." (PMID 36497117, 2022). "In addition, suppression of GADD45A sensitized melanoma cells to cisplatin and enhanced cisplatin-induced DNA damage." (PMID 29515153, 2018). "It suggested that GADD45A could be involved in cisplatin response and may be a new target for melanoma treatment." (PMID 29515153, 2018). "The expression of GADD45A in melanoma might increase DNA repair and thus protect melanoma from cisplatin-induced DNA damage." (PMID 29515153, 2018). "It suggested that MAPK-ERK activation may be critical in regulating the expression of GADD45A following cisplatin treatment in melanoma cells." (PMID 29515153, 2018). "Moreover, STX140 induced senescence features in melanoma and activated the senescence machinery by upregulating the expression of senescence genes, such as CDKN1A e GADD45A in resistant melanoma and proteins related to senescence signaling, such as p21 (only in SKMEL-28R) and γH2AX." (PMID 37511073, 2023). "However, whether cisplatin induce GADD45A expression in melanoma cells and its role in chemotherapy response is still unclear." (PMID 29515153, 2018). "Inactivation of GADD45A could release melanoma cells from cell cycle arrest and enhance apoptosis." (PMID 29515153, 2018). "GADD45A expression may be involved in cisplatin response in melanoma cells." (PMID 29515153, 2018). "Thus, the induction of GADD45A might play important roles in chemotherapy response in human melanoma cancer and could serve as a novel molecular target for melanoma therapy." (PMID 29515153, 2018).
melanoma (continued). "A microarray analysis of the syngeneic murine melanoma model B16F10 upon a dual treatment of carbon-ion external radiotherapy and 131I-Benzamide showed an enrichment of the genes PARP3, MDM2, GADD45A, which were also found to be upregulated in our study." (PMID 34830750, 2021). "We then validated the transcriptional expression of key candidate genes such as CDKN1A (P21), GADD45A, and MCM3 after this compound treatment and knocking down Fyn expression in melanoma cells." (PMID 32565740, 2020). "Consistent with the sequencing results, RT-PCR confirmed that GADD45A and CDKN1A were upregulated in the Lj-1-60-treated group, while minichromosome maintenance 3 (MCM3) was downregulated in melanoma cells Sk-Mel-5 and Sk-Mel-28." (PMID 32565740, 2020). "In addition to several ECM proteins that were found to be downregulated we also observed upregulation of several pro-apoptotic genes such as BAX, CDKN1A, GADD45A, GADD45B, etc. in TP-472–treated melanoma cells." (PMID 34771678, 2021). "We additionally confirmed the expression with mRNA levels of key genes after treatment with lj-1-59 in melanoma cells, which indicated that P21, BBC3, SESN2 and GADD45A expression were significantly upregulated, while MCM2, MCM3, MCM4, MCM7 and PKMYT1 were significantly downregulated." (PMID 32021565, 2020). "Furthermore, we verified key gene expression with mRNA levels after treatment with VB1 in melanoma cells, which indicated that the P21, PUMA and GADD45A expression was significantly upregulated and that the expression of MCM6, CDK1, CDK6, CYCE and CYCA was significantly downregulated." (PMID 30400954, 2018). "To further analyze the role of GADD45A in cisplatin response, we transfected melanoma A375 and SK-MEL-28 cells with small interfering RNA (siRNA) of GADD45A: cells were transfected with negative control (NC), GADD45A siRNA-387 or GADD45A siRNA-564." (PMID 29515153, 2018).
hepatocellular carcinoma (15 papers, 2013 to 2025). A malignant tumor that arises from hepatocytes. "GADD45A is upregulated in liver cirrhosis (LC), hepatocellular carcinoma (HC), acute hepatic failure (AHF), and non‐alcoholic fatty liver disease (NAFLD)." (PMID 40548900, 2025). "In hepatocellular carcinoma (HCC), sCLU is markedly overexpressed, contributing to resistance against oxaliplatin by downregulating Gadd45a expression and activating the PI3K/Akt pathway." (PMID 38667280, 2024). "sCLU is highly overexpressed in hepatocellular carcinoma (HCC) and contributes to oxaliplatin resistance by downregulating the expression of Gadd45a and activating the PI3K/Akt pathway." (PMID 37685987, 2023).
lung carcinoma (13 papers, 2008 to 2024). "In the current study, we reveal that nuclear C3b acts as a cofactor of the chromatin remodeling SIN3A complex to repress the expression of GADD45A, thus conferring acquired resistance of lung cancer to PTX treatment." (PMID 37291119, 2023). "In lung cancer, curcumin treatment increased GADD45A expression, which leads to the reduction of cell proliferation rate." (PMID 34366863, 2021). "Thus, we speculate that PtpA might potentially contribute to lung cancer development during chronic Mtb infection through regulating the transcription of certain checkpoint protein-coding genes (such as GADD45A) and ncRNAs." (PMID 28811474, 2017). "In this study, transcriptome profiling and RT-qPCR validation revealed that PGL arrests the cell cycle via downregulation of the expression of RB1, CCNH, MDM2, ACCN4, CCND2, GADD45A, and GADD45B in lung cancer cells." (PMID 27355352, 2016).
colorectal cancer (12 papers, 2015 to 2025). A primary or metastatic malignant neoplasm that affects the colon or rectum. "For example, the expression of GADD45A in tumor tissue from colorectal cancer patients was significantly downregulated compared with normal mucosa tissue." (PMID 40236773, 2025). "The SATB2-AS1 recruits WDR5 and GADD45A to the SATB2 promoter and catalyzes DNA demethylation and histone 3 lysine 4 trimethylation to prohibit colorectal cancer cells’ progression." (PMID 40961095, 2025). "SATB2-AS1 is the cognate antisense transcript of SATB2, and SATB2-AS1 activates SATB2 in cis by recruiting WDR5 and GADD45A to the SATB2 promoter region and inhibits the progression of colorectal cancer." (PMID 36056355, 2022). "LncRNA SATB2-AS1 enhances the transcription of SATB2 by binding to growth arrest and DNA damage-inducible protein GADD45 alpha (GADD45A) and WD repeat-containing protein 5 (WDR5), which in turn inhibits the metastasis of colorectal cancer." (PMID 34830378, 2021). "GADD45A acts as a tumour suppressor and was found to be correlated with the expression of the core-clock gene PER2, in human colorectal carcinoma tissues." (PMID 34885088, 2021).
ovarian carcinoma (12 papers, 2014 to 2026). A malignant neoplasm originating from the surface ovarian epithelium. "To test the prognostic power of the GADD45A polymorphism in ovarian cancer, we calculated the GADD45A genotype with respect to ovarian relapse-free survival (RFS) and overall survival (OS)." (PMID 26422378, 2015). "We are the first group to demonstrate that the GADD45A (1506T>C) polymorphism is associated with ovarian cancer susceptibility and prognosis." (PMID 26422378, 2015). "In this study, the GADD45A (1506T>C) polymorphism was found to be associated with the ovarian cancer risk, clinicopathological characteristics, GADD45A expression levels and ovarian cancer prognosis." (PMID 26422378, 2015). "In this study, for the first time, we demonstrate that the GADD45A (1506T>C) polymorphism is associated with ovarian cancer susceptibility and prognosis." (PMID 26422378, 2015). "Studies indicated GADD45A was associated with ovarian cancer susceptibility and prognosis." (PMID 36905391, 2023). "Overexpression of GADD45A may be implicated in the pro-apoptosis effect of the synthetic retinoid CD437 on ovarian cancer cells." (PMID 28407786, 2017). "We expect GADD45A to be a useful molecular marker for assessing ovarian cancer risk and prognosis." (PMID 26422378, 2015). "In conclusion, we found, for the first time, that the GADD45A (1506T>C) polymorphism may be correlated with ovarian cancer susceptibility, clinicopathological characteristics, GADD45A expression levels and ovarian cancer prognosis." (PMID 26422378, 2015). "The variants of GADD45A may prove to be useful markers for the identification of ovarian cancer-susceptible patients or prognostic indicators of disease progression, and they may also serve as potential targets for future therapies." (PMID 26422378, 2015). "Thus, we investigated the GADD45A (1506T>C) polymorphism, GADD45A expression, and ovarian cancer risk and prognosis." (PMID 26422378, 2015). "In ovarian cancer cell lines, 1,25(OH)2D3 increased GADD45α (Growth arrest and DNA-Damage-Inducible alpha) and subsequently induced cell cycle arrest at the G2/M phase." (PMID 33291213, 2020). "The levels of GADD45A mRNA in 22 ovarian cancer tissues were significantly lower than the levels observed in 15 normal tissues (P<0.001)." (PMID 26422378, 2015). "Carrying the T allele (TT+TC) showed a significant correlation with both higher GADD45A mRNA expression and longer ovarian cancer RFS (relapse-free survival) and OS (overall survival)." (PMID 26422378, 2015). "The induction of GADD45A expression might play a role in mediating the apoptotic response of ovarian cancer cells to the synthetic retinoid CD437." (PMID 26422378, 2015).
colon carcinoma (11 papers, 2010 to 2025). "Lastly, we excluded a role for somatic and germline GADD45A mutations in the tumorigenesis of early onset sporadic MSI-H colon cancer." (PMID 20444249, 2010). "The absence of pathogenic somatic and germline mutations in human GADD45A observed in our study and data published during this study suggest that a role for GADD45A mutations in aberrant hypermethylation in human colon tumors is unlikely." (PMID 20444249, 2010). "It had been reported that baicalein could induce the apoptosis of colon cancer cells through inducing DEPP/Gadd45a and activating MAPKs." (PMID 33777154, 2021). "Somatic or germline GADD45A mutations did not explain sporadic MSI-H colon cancer." (PMID 20444249, 2010). "Specific short interfering RNA (siRNA)-mediated knockdown of GADD45A and GADD45B in the colon cancer cell line RKO induced hypermethylation of MLH1, THBS1 and p16, three genes known to be involved in carcinogenesis of different types of tumors by DNA methylation." (PMID 20444249, 2010).